TFRC (transferrin receptor)
Diseases named in the same sentence as TFRC in open-access papers (continued):
Sharing a sentence is not in itself a finding about the gene and the disease.
iron deficiency (continued). "The association between the two independent indicators of iron-deficient erythropoiesis (i.e. haemoglobin and soluble transferrin receptor concentration) identified ferritin concentration thresholds of ~ 20 μg/L and ~ 25 μg/L to define iron deficiency in children and nonpregnant women, respectively." (PMID 39010146, 2024). "Under iron deficiency conditions, binding of IRPs to IREs inhibits the translation of mRNAs with 5′-IRE stem loops such as ferritins and ferroportin (FPN), whereas it stabilizes the mRNAs that contain 3′-IREs such as the transferrin receptor (TfR1) and divalent metal transporter (DMT1)." (PMID 38732071, 2024). "In addition, many iron deficiency indicators associated with frailty, such as serum ferritin, soluble transferrin receptors (sTfR) or transferrin saturation, were not studied in the NHANES database in the elderly." (PMID 37805459, 2023). "However, serum iron concentrations and soluble transferrin receptor-1 (sTfR), a marker of iron deficiency and ineffective erythropoiesis, have been reported to be normal, confirming the iron is sufficient for hemoglobin synthesis in EPP." (PMID 35309058, 2022). "Serum transferrin receptor level and hepcidin may be useful for distinguishing anemia of inflammation from iron deficiency anemia (IDA), but these tests are not widely available." (PMID 36422508, 2022). "Ferritin and soluble transferrin receptor levels which are better indicators of iron stores and iron deficiency than hemoglobin and transferrin were not measured due to logistic constraints and the analysis for anemia were not adjusted for inflammatory markers like C-reactive proteins." (PMID 34493339, 2021). "This may be related to the lower prevalence of iron deficiency, as defined by ferritin and serum transferrin receptor concentrations (4–8% rather than 24% in Gambian children)." (PMID 32276153, 2020). "Until recently, the soluble transferrin receptor (sTfR) was the best parameter in assessing iron deficiency in cystic fibrosis, based on which the sTfR (μg/mL) to the logarithm of serum ferritin (mg/L) (TfR/logFer) ratio is calculated, as these values are not inflammation-dependent." (PMID 30057485, 2018). "While intramyocellular iron deficiency may ensue, it is not likely that the muscular down regulation of TFRC was secondary to systemic iron deficiency." (PMID 28784116, 2017). "Finally, it would have been ideal to include assessment of soluble transferrin receptor concentration since this biomarker reflects iron deficiency and is not affected by infection or inflammation." (PMID 26880234, 2016). "In contrast, multiple IREs in the 3′-UTR (as in transferrin receptor 1) allow for stabilization and accumulation of specific mRNAs through IRP binding, resulting in more mRNA to be translated, more protein, and in the case of transferrin receptor 1, uptake of more iron to remedy iron deficiency." (PMID 24152745, 2013). "Due to nonspecific utilization of plasma transferrin receptor concentration in older individuals, TSAT was used as an indicator of iron deficiency in this study." (PMID 32901103, 2021). "Other parameters of iron metabolism, such as serum iron, total iron-binding capacity (TIBC), transferrin saturation (TSAT), soluble transferrin receptor (sTfR), zinc protoporphyrin (ZPP), or hepcidin, can support the diagnosis of iron deficiency, but their use is not recommended for diagnosis." (PMID 40270491, 2025).
anemia (294 papers, 2003 to 2026). A reduction in the number of red blood cells, the amount of hemoglobin, and/or the volume of packed red blood cells. "Among women, low ferritin and elevated serum transferrin receptor (sTfR) levels were associated with higher odds of anemia, whereas overweight status, higher gravidity, and vitamin B12 deficiency were associated with lower odds." (PMID 41829921, 2026). "Inadequate serum ferritin (OR = 11.931, 95% CI = 4.846 ~ 29.379), excessive serum transferrin receptor (OR = 1.817, 95% CI = 1.050 ~ 3.145) and anemia during pregnancy were risk factors for anemia." (PMID 39931365, 2025). "Progression of anemia in MM has been associated with worsening erythroid hypoplasia, indirectly marked by transferrin receptor levels." (PMID 35334593, 2022). "Serum transferrin receptor (sTfR) levels and the ratio of sTfR/serum ferritin has been proposed as a differential diagnostic marker between anemia caused by chronic iron deficiency vs chronic inflammation." (PMID 35943990, 2022). "The molecules engaged in iron metabolism, namely hepcidin and soluble transferrin receptor (sTfR), have been previously suggested as potential biomarkers in MM, enabling to better characterize the underlying etiology of anemia." (PMID 35334593, 2022). "Associations between anaemia and maternal, child and household variables, and biomarkers (soluble transferrin receptor, ferritin, zinc, folate, vitamin B12, C‐reactive protein, and α1‐acid glycoprotein) were explored." (PMID 31595712, 2020). "Previous studies were mostly in cross-sectional design and did not evaluate the diagnostic value of hepcidin or ferritin or transferrin receptor for detection of anemia in pregnancy." (PMID 33101731, 2020). "Prevalence of deficiency among all participants was as follows: anemia, 20.6%; iron by ferritin, 4.0%; iron by transferrin receptor, 4.7%; folate, 2.5%; vitamin B-12, 35.4%; vitamin A, 6.7%; vitamin E, 57.7%; vitamin D, 64.0%; zinc, 13.4%; and iodine, 2.6%." (PMID 31006806, 2019). "We previously found that CALM-deficient mice suffer from severe anemia due to the impaired clathrin-mediated endocytosis of transferrin receptor in immature erythroblast." (PMID 25279552, 2014). "Anemia of inflammation, hypoferremia, poor transferrin saturation, and high levels of serum ferritin, hepcidin, lipocalin-2, catalytic iron, and soluble transferrin receptor (in ICU patients) have all been iron-associated changes in COVID-19 from the beginning." (PMID 37763241, 2023). "Using data from 1283 children in the MAL-ED (Etiology, Risk Factors, and Interactions of Enteric Infections and Malnutrition and the Consequences for Child Health) birth cohort we evaluated the risk of anemia, low retinol, zinc, and ferritin, and high transferrin receptor (TfR) at 15 mo." (PMID 31565748, 2019). "Combined with the evidence from previous studies, serum ferritin and transferrin receptor, which reflect iron reserves, can provide early warning of the occurrence of anemia." (PMID 39931365, 2025). "The results showed that taking iron supplements during pregnancy, sufficient intake of red meat, and normal serum ferritin and transferrin receptor levels were protective factors for anemia in postpartum women." (PMID 39931365, 2025). "Laboratory testing for ferritin, transferrin, transferrin receptor and CRP can help distinguish between inflammation-induced anemia and iron-deficiency related anemia but rarely allows for a definitive diagnosis in intermediate cases." (PMID 40636681, 2025). "The results indicated that taking iron supplements during pregnancy, sufficient intake of red meat, and normal serum ferritin and transferrin receptor levels were protective factors against anemia in postpartum women." (PMID 39931365, 2025). "Results showed plasma soluble transferrin receptor /log ferritin ratios that elevated in the P group denoting anemia was reduced in the test groups; with superiority to Sb." (PMID 40615531, 2025).
anemia (continued). "Blood Hb, Hep, and Soluble Transferrin receptor (sTfR) are used to address anemia and the iron balance." (PMID 40650185, 2025). "The determination of the soluble transferrin receptor/log ferritin ratio (sTfR-F index) provides a significant advantage in diagnosing the type of anemia." (PMID 39684440, 2024). "This resulted in moderate anemia with increased plasma erythropoietin and soluble transferrin receptor levels." (PMID 37234375, 2023). "This review's main strength is that it provides insights into the effect of iron on a wide range of outcomes, including hemoglobin, serum ferritin, iron, transferrin receptor, and anemia prevalence." (PMID 37069552, 2023). "Zinc supplementation had an adverse effect on serum ferritin, plasma/serum copper concentration, serum transferrin receptor, hemoglobin, hematocrit, and the odds of anemia in ≥1 of the subgroups investigated." (PMID 36055780, 2022). "Open defecation (AOR 2.36, 95% CI [1.15, 4.84]) and ln transferrin receptor [mg/L] (AOR 3.21, 95% CI [1.25, 8.23]) were associated with increased anaemia odds." (PMID 32338438, 2022). "To rule out the putative role of iron status, we also measured transferrin and soluble transferrin receptor in order to discard subclinical anemia due to higher hepcidin on the one hand, and iron overload on the other." (PMID 34065056, 2021). "In the study of factors contributing to anemia, it is imperative to assess nutritional biomarkers such as ferritin, transferrin receptor, zinc, and others." (PMID 33017433, 2020). "This study aimed at defining the best marker among ferritin, hepcidin, or soluble transferrin receptor (sTfR) in the first trimester for prediction of anemia in the third trimester." (PMID 33101731, 2020). "But if the mother has anemia during pregnancy, maternal iron storage decreases, transferrin receptor compensatory conversely increases, and the placental iron uptake capacity decreases." (PMID 31993152, 2020). "Anemia and serum transferrin receptor at time of vaccination were the strongest predictors of seroconversion against diphtheria (p = 0.0484, p = 0.0439) and pneumococcus 19 at 18 mo (p = 0.0199, p = 0.0327)." (PMID 32754150, 2020). "Of those students with anaemia in the weighted population, serum ferritin was normal but transferrin receptor was raised in 29.9% males and 12.4% females." (PMID 29155855, 2017). "Indicators of inflammation, malaria, anemia, and micronutrient status [plasma ferritin, soluble transferrin receptor (sTfR), zinc, folate, and vitamin B-12] were assessed among women aged 15–49 y and children 12–59 mo of age." (PMID 28592513, 2017). "Total body iron, calculated from serum ferritin and soluble transferrin receptor concentrations, and hemoglobin allow for monitoring of the iron and anemia status of children in the United States." (PMID 27249004, 2016). "Compounding these challenges, most large‐scale epidemiological studies in the Andean rely solely on Hb measurements to diagnose anemia, overlooking critical iron biomarkers (e.g., ferritin and serum transferrin receptor) and inflammation markers (e.g., CRP and IL‐6)." (PMID 40600692, 2025). "The severe anemia observed in hpx/hpx mice and patients with hereditary atransferrinemia indicates that when the Tf-Fe2+-transferrin receptor 1 (TfR1) cycle pathway is unable to function properly, it results in a reduction of iron entering erythroid precursors." (PMID 38500764, 2024). "Demographics, inflammatory markers (interleukins 6 and 10, hepcidin), nutritional status (mid upper-arm circumference and body mass index), and anaemia (total haemoglobin, ferritin, soluble transferrin receptor) were assessed as potential predictors through logistic regression." (PMID 37658365, 2023). "The researchers noticed maternal anemia (defined as a hemoglobin level below 11 g/dL) in 40% of cases, but it did not correlate with newborn iron biomarkers, such as serum ferritin, soluble transferrin receptor, or hepcidin." (PMID 37764830, 2023).
anemia (continued). "In these situations, other clinical tests, such as the serum iron, transferrin saturation, soluble transferrin receptor (sTfR), sTfR /log ferritin or C-reactive protein, may be useful adjunctive tests to assist in the diagnosis anemia." (PMID 36823529, 2023). "We further hypothesize that the activation of the innate immune system in MMVD may result in anemia of chronic disease and decreased abundance of transferrin receptor protein 1 with disease progression." (PMID 37108311, 2023). "In the matched nested case–control study (256 women), hemoglobin (Hb), serum ferritin (SF) and the SF/soluble transferrin receptor ratio at T1 were predictive of anemia at T3 (p < 0.001); however, clinical and social characteristics, as serum hepcidin were not." (PMID 36235743, 2022). "Soluble TFRC is elevated in acute states and constitutes a marker of Fe deficiency in tissues rather than a measure of anemia." (PMID 35327526, 2022). "Our aim is to evaluate the biomarkers of iron turnover: serum soluble transferrin receptor (sTfR) and hepcidin-25 in patients at various stages of MM in relation with markers of anemia, iron status, inflammation, renal impairment and burden of the disease and as predictors of mortality." (PMID 35334593, 2022). "Secondary outcomes analyzed were preterm births, serum/plasma hemoglobin (g/L), infant mortality, serum/plasma transferrin receptor (mg/L), neonatal mortality and serum/plasma ferritin (ug/L) For Iron vs. Placebo, the primary outcomes were low birth weight, maternal anaemia and perinatal mortality." (PMID 37051178, 2021). "New biomarkers of ferric management, namely, soluble transferrin receptor (sTfR), growth differentiation factor 15 (GDF15) and hepcidin 25, may correlate with characteristics in the etiology and management of MM-associated anaemia." (PMID 31683939, 2019). "Due to constraint of resource, we were unable to measure serum ferritin concentration, soluble transferrin receptor concentration, folate levels, vitamin B12 levels, thalassemia, and G6PD deficiency; which could have helped in finding the causes of anemia." (PMID 31276472, 2019). "Earlier on the traces of one more marker of reticulocytes, CD71 (transferrin receptor), were reported to be associated not with RBCs, but with vesicles in serum of horses recovering from anemia caused by phlebotomy." (PMID 31379601, 2019). "Transferrin receptor 1 (TfR1), which is highly expressed in piglets with anemia, may play a role in TGEV infection." (PMID 30342530, 2018). "Therefore, further research should be undertaken to verify the prevalence of ID/anaemia, preferably not only based on measures of haemoglobin but also of other iron status biomarkers such as ferritin and soluble transferrin receptor." (PMID 30545329, 2018). "In a previous study from our laboratory (unpublished data), we showed that Senegalese outpatients PLWH with anemia were not iron deficient according to their plasma ferritin concentration or serum transferrin receptor." (PMID 26728978, 2016). "More directly, erythroblasts are themselves significantly dependent on proper iron homeostasis controlled by IRP2 and on successful iron acquisition mediated by transferrin receptor 1 (TfR1) and mitoferrin-1 (or SLC25A37), as shown by anemias that develop when they are deficient in model organisms." (PMID 20862391, 2010). "Lack of measurements of serum indexes such as serum ferritin and transferrin receptor may have limited our understanding of the true prevalence of anemia." (PMID 19754927, 2009). "After adjusting for age; sex; race/ethnicity; body mass index; smoking status; and levels of albumin, creatinine, ferritin, and transferrin receptor, a nonlinear (U-shaped) association was observed between Mn levels and anemia risk (P < 0.001 for nonlinearity)." (PMID 40740730, 2025).
anemia (continued). "We hypothesized that the egg intervention group would have higher mean concentrations of hemoglobin and ferritin, lower mean soluble transferrin receptor (sTfR), and lower prevalence of ID, anemia, and IDA as compared with the control group after the intervention period." (PMID 35755939, 2022). "Elevated ferritin level, serum transferrin, transferrin receptor (TfR), TIBC, erythrocyte sedimentation rate, and C-reactive protein concentrations, and reduced serum iron concentrations and transferrin saturation are usually associated with anemia of chronic disease." (PMID 30237895, 2018). "The increased anaemia that was observed in infected Gx female mice could be potentially explained by their increased NO levels because it has been shown that NO inhibits haem synthesis and iron uptake via the transferrin receptor pathway." (PMID 25243182, 2014). "From a public health perspective, our results advocate for integrated anaemia screening in obese populations that includes inflammation‐corrected iron markers (e.g., BRINDA‐adjusted ferritin, soluble transferrin receptor) and CRP or hepcidin measurements." (PMID 40968580, 2025). "Further characterization of the anemia of the mRNA of livers of IRAG1-WT and IRAG1 mice were investigated regarding hepcidin (Hamp) and transferrin receptor 1 (Tfr1)." (PMID 34064290, 2021). "The anemia was explained by apoptosis of fetal liver cells and reduced expression of iron-regulatory protein 2 (IRP2) and transferrin receptor 1 (TFR1)." (PMID 31690038, 2019). "Anaemia was defined as serum haemoglobin < 11 g/dL and IDA was defined by serum haemoglobin < 11 g/dL, serum ferritin < 12 g/L and soluble transferrin receptor > 8.3 mg/L." (PMID 32084025, 2019). "Four surveys were conducted to evaluate Knowledge, Attitudes and Practices (KAP) towards anaemia and IFA tablets, and to collect haematological parameters with haemoglobin, ferritin, and soluble transferrin receptor being assessed by national institutes." (PMID 29271119, 2018). "Secondary iron parameter measurements including serum ferritin, TSAT, and serum transferrin receptor levels were significantly better in FCM, and more women were likely to achieve anemia correction with FCM as well." (PMID 30153811, 2018). "Serum transferrin receptor concentration is increased in IDA, but is normal in anemia of chronic disease." (PMID 26261697, 2015). "The incidence of anemia among 4 major cancers (gastric, colorectal, lung cancer and hepatocellular carcinoma), and biochemical features of anemia using ferritin, CRP, hepcidin and soluble transferrin receptor (sTfR) were assessed." (PMID 26517509, 2015). "The serum levels of the soluble transferrin receptor (sTfR) are strongly increased in patients with AID, but reduced in those with ACD and chemotherapy-induced anemia, making this parameter unsuitable for the assessment of iron homeostasis." (PMID 26373748, 2015). "In contrast to ferritin, soluble transferrin receptor (sTfR) concentrations remain largely unaffected by chronic inflammatory states, which makes it a more specific biomarker for distinguishing between IDA and anemia of chronic disease (ACD)." (PMID 41384201, 2025). "Notably, a subset of splenic HSCs expressed CD71, the transferrin receptor enriched in erythroid cells, after PHZ-induced anemia." (PMID 38225226, 2024). "Studies with Stat5a/b-/- mice demonstrate that both STAT5a and STAT5b are critical regulators of iron uptake during erythroid development, as the absence of both STAT5 proteins resulted in severe anemia and reduction of Tfr1 expression (transferrin receptor)." (PMID 36755813, 2022). "Transferrin levels and soluble transferrin receptor were not different between the groups, discarding subclinical anemia." (PMID 34065056, 2021). "Neither high TFRC mRNA nor TFRC protein levels in AML cells correlated with patient outcome although a correlation was found with increased anemia, thrombopenia and complex cytogenetics." (PMID 33679722, 2020).